EIF2AK3 (eukaryotic translation initiation factor 2 alpha kinase 3)
Diseases named in the same sentence as EIF2AK3 in open-access papers (continued):
Sharing a sentence is not in itself a finding about the gene and the disease.
Wolcott-Rallison syndrome (57 papers, 2007 to 2026). Wolcott-Rallison syndrome (WRS) is a very rare genetic disease, characterized by permanent neonatal diabetes mellitus (PNDM) with multiple epiphyseal dysplasia and other clinical manifestations, including recurrent episodes of acute liver failure. "Neutropenia is one of the symptoms of Wolcott-Rallison syndrome caused by mutations in PERK, encoded by the EIF2AK3 gene, and heightened ER stress was reported in neutropenias caused by mutations in ELANE and glucose-6-phosphate subunit α gene (G6PC3)." (PMID 39962231, 2025). "In a consanguineous population, the most prevalent genetic cause was a homozygous mutation in the EIF2AK3 gene, which result in 24% of them were affected with Wolcott-Rallison syndrome." (PMID 34584998, 2021). "Wolcott-Rallison syndrome (WRS) is caused by a biallelic mutation in the gene encoding eukaryotic translation initiation factor 2-alpha kinase 3 (EIF2AK3) on chromosome 2p11.2." (PMID 30922274, 2019). "Previous studies showed that loss-of-function mutations in EIF2AK3 resulted in Wolcott-Rallison Syndrome in humans and that EIF2AK3-deficient (Perk−/−) mice also exhibited skeletal dysplasias at birth and postnatal growth retardation." (PMID 31351448, 2019). "Mutations in PERK (EIF2AK3) cause a complex genetic disorder of the Wolcott Rallison syndrome with permanent neonatal diabetes characterized by β cell depletion." (PMID 28845211, 2017). "We identified recessive mutations in EIF2AK3, which confirm a genetic diagnosis of Wolcott-Rallison syndrome, in 76 patients." (PMID 26231457, 2015). "Wolcott-Rallison syndrome is caused by biallelic mutations in EIF2AK3, a gene known to be important for regulation of endoplasmic reticulum stress." (PMID 26231457, 2015). "A deficiency in Perk (EIF2AK3) causes multiple neonatal defects in humans known as the Wolcott Rallison syndrome." (PMID 19732428, 2009). "The adaptive nature of the ISR during embryogenesis is exemplified by Wolcott-Rallison syndrome, a human disorder in which homozygous loss-of-function mutations in the gene encoding PERK (EIF2AK3) result in neonatal diabetes; this phenotype is mirrored in Eif2ak3–/– mice." (PMID 38889047, 2024). "A 3-month-old Arab female infant presented with neonatal DM, epiphyseal dysplasia, and liver failure; she was diagnosed with Wolcott-Rallison syndrome caused by the pathogenic homozygous mutation of c.1293G > A (p.W431*) in EIF2AK3, which was previously reported to be pathogenic." (PMID 33663443, 2021). "In humans, the loss of function mutations in the EIF2AK3 gene, which encodes PERK, cause Wolcott-Rallison syndrome (WRS)." (PMID 34360909, 2021). "In this study, clinical diagnosis of Wolcott-Rallison Syndrome (WRS) was confirmed by the identification of a novel homozygous missense mutation (Q166R) in exon 3 of the EIF2AK3 gene." (PMID 24032041, 2013). "Mutations in EIF2AK3, encoding PERK, cause Wolcott-Rallison syndrome, an autosomal recessive neurodevelopmental disease characterized by ID and infancy-onset diabetes." (PMID 40719631, 2025). "Two siblings, born to related parents, were referred to the Exeter genomics laboratory for genetic testing on suspicion of Wolcott Rallison syndrome, a disorder caused by recessive variants in the EIF2AK3 gene that encodes a regulator of ER proteostasis, PERK." (PMID 36704923, 2023). "The most common monogenic PNDM subtype is Wolcott-Rallison syndrome (WRS; OMIM 226980) and is caused by recessive missense and truncation mutations in the EIF2AK3 gene, which encodes the eIF2 alpha kinase, PERK." (PMID 35579296, 2022). "EIF2AK3 (OMIM#604032), which causes Wolcott-Rallison syndrome, is another gene typically involved in PNDM." (PMID 34584998, 2021). "Similar phenomena are also seen in PERK-deficient mice and in the rare human disorder Wolcott-Rallison syndrome, which presents with neonatal diabetes due to loss-of-function mutations in the PERK gene EIF2AK3." (PMID 27190028, 2016).
Wolcott-Rallison syndrome (continued). "Anti-GAD was negative, and Wolcott Rallison syndrome was confirmed by the detection of two homozygous EIF2AK3 mutations." (PMID 32820876, 2021). "Recessive mutations in EIF2AK3, encoding PERK, give rise to Wolcott-Rallison syndrome." (PMID 28951826, 2017). "Furthermore, mutations in EIF2AK3 lead Wolcott-Rallison-syndrome (WRS), an extremely rare condition with complete absence of PERK which is associated with neurodegeneration." (PMID 35695938, 2022). "Moreover, mutations in the EIF2AK3 gene (encoding PERK) were associated to the rare genetic disease, Wolcott-Rallison Syndrome (WRS)." (PMID 33530161, 2021). "Case 10 (EIF2AK3 p.C532STOP) was accompanied with intellectual and physical retardation, short stature, multiple skeletal dysplasia, and hypothyroidism, diagnosed as Wolcott-Rallison syndrome." (PMID 26839896, 2016). "The gene for Wolcott-Rallison syndrome (WRS), EIF2AK3, was also sequenced but returned a negative result." (PMID 24778889, 2014).
glioma (48 papers, 2011 to 2025). A benign or malignant brain and spinal cord tumor that arises from glial cells (astrocytes, oligodendrocytes, ependymal cells). "The results showed that WHO IV and WHO III gliomas had significantly higher EIF2AK3 mRNA expression than WHO II." (PMID 37153540, 2023). "Next, we used tissue microarrays containing 12 cancerous and 70 diffuse glioma samples to measure EIF2AK3 expression in gliomas via IHC staining." (PMID 37153540, 2023). "EIF2AK3 mRNA expression levels were significantly higher in glioma tissues than in tissues adjacent to carcinomas (P < 0.05)." (PMID 37153540, 2023). "To validate the expression of EIF2AK3 in glioma samples, we detected a series of glioma samples from Xiangya Hospital." (PMID 37153540, 2023). "We first measured the mRNA expression level of EIF2AK3 in glioma tissues and corresponding para-carcinoma tissues in seven patients via RT-qPCR." (PMID 37153540, 2023). "Then, we detected EIF2AK3 mRNA expression in 72 glioma samples of different grades." (PMID 37153540, 2023). "The experimental results indicated that EIF2AK3 expression was higher in tumors than paracancerous tissues, and high-expression EIF2AK3 was enriched in WHO III and IV gliomas by qPCR and IHC, and Knockdown of EIF2AK3 suppressed cell viability and mobility in glioma cells." (PMID 37153540, 2023). "EIF2AK3, best known as PERK, was reported to promote glioma cell viability, migration, and anti-apoptosis in vitro." (PMID 37153540, 2023). "Moreover, EIF2AK3 enrichment was observed in lower-grade gliomas (LGG), and its knockdown significantly inhibited glioma cell viability and motility." (PMID 41150760, 2025). "We found the expression of EIF2AK3 protein was significantly higher in WHO grades III (P < 0.05) and IV gliomas (P < 0.001) compared to WHO II gliomas (P < 0.05); However, the difference in EIF2AK3 protein expression between WHO II glioma and para-carcinoma tissues were not significant." (PMID 37153540, 2023). "EIF2AK3, the gene coding for PERK, is overexpressed in GBM compared to non-tumoral brain tissue but not in the other two gliomas subtypes." (PMID 31795417, 2019).
lung carcinoma (44 papers, 2014 to 2025). "Significantly, EIF2AK3/PERK has been recognized as one of the ER-resident sensors associated with the risk of lung cancer." (PMID 41353169, 2025). "We found that EIF2AK3-rs6750998 polymorphism was associated with a decreased risk of lung cancer under dominant, recessive, and log-additive models (p < 0.05)." (PMID 35923704, 2022). "In conclusion, we found that EIF2AK3-rs6750998 was a protective variant against the risk of lung cancer, while EIF2AK3-rs867529, HSPA5-rs391957, and DDIT3-rs697221 were all susceptible variants for the disease." (PMID 35923704, 2022). "In addition, EIF2AK3-rs6750998 was associated with a decreased risk of lung cancer under dominant, recessive, and log-additive models (p < 0.05)." (PMID 35923704, 2022). "However, little information is found about the single-nucleotide polymorphisms (SNPs) in EIF2AK3/PERK, HSPA5/GRP78, and DDIT3/CHOP in cancer patients, especially those with lung cancer." (PMID 35923704, 2022).
tauopathies (41 papers, 2013 to 2026). "Population studies implicate EIF2AK3 (eukaryotic translation initiation factor 2 alpha kinase 3), better known as PERK (protein kinase R-like endoplasmic reticulum kinase), as a genetic risk factor in several tauopathies." (PMID 36563857, 2023). "However, using human induced pluripotent stem cells (iPSC) carrying the PERK B risk variant associated with tauopathies, we discovered that ER stress induced via tunicamycin showed that mutation of the EIF2AK3 gene resulted in a hypomorph." (PMID 34360909, 2021). "EIF2AK3 (eukaryotic translation initiation factor 2 alpha kinase 3), more commonly known as PERK (protein kinase R-like endoplasmic reticulum kinase), is a genetic risk factor for tauopathies: PSP and AD." (PMID 36563857, 2023). "Further, variants of the EIF2AK3 gene that encodes PERK and polymorphisms in the XBP1 gene associated with altered transcriptional activity have been identified as genetic risk factors for tauopathies." (PMID 32707908, 2020).
Hyperglycemia (37 papers, 2009 to 2025). An increased concentration of glucose in the blood. "Eif2ak3–/– mice developed similar phenotypes with hyperglycemia, hypoinsulinemia, ER stress, β-cell loss, misfolded insulin, and defects in the secretory pathway causing accumulation of proinsulin in the ER." (PMID 38744890, 2024).
Alzheimer disease (34 papers, 2010 to 2025). A progressive, neurodegenerative disease characterized by loss of function and death of nerve cells in several areas of the brain leading to loss of cognitive function such as memory and language. "ADAM17, BACE1, CAPN1, CDK5, EIF2AK3, GRIN2B, and GSK3B were enriched in the Alzheimer disease pathway (hsa05010)." (PMID 33807157, 2021).
Hepatic steatosis (33 papers, 2012 to 2026). Steatosis is a term used to denote lipid accumulation within hepatocytes. "On the other side, thapsigargin was found to promote the phosphorylation of EIF2AK3, which was markedly reduced by overexpression of Hspa5 in hepatic steatosis in mice." (PMID 39000233, 2024).
gastric cancer (29 papers, 2014 to 2025). A primary or metastatic malignant neoplasm involving the stomach. "The distribution of mutations of 133 UPR related genes in stomach cancer were exhibited in waterfall plot, it is estimated that EIF4G1, DDX10, and EIF2AK3, which have the highest mutation rate, have a mutation rate of 4%, and the mutation type is predominantly missense mutations." (PMID 38700505, 2024).
myeloma (28 papers, 2011 to 2026). "PERK, encoded by the EIF2AK3 gene, is expressed ubiquitously in normal tissues (albeit at higher levels in secretory tissues such a pancreatic islet cells) and is also present and active in hematologic malignancies, including multiple myeloma (MM) and chronic myeloid leukemia (CML)." (PMID 36348393, 2022).
leukemia (27 papers, 2002 to 2026). A malignant (clonal) hematologic disorder, involving hematopoietic stem cells and characterized by the presence of primitive or atypical myeloid or lymphoid cells in the bone marrow and the blood. "EIF2AK3 (also named as PKR-like endoplasmic reticulum kinase, PERK) is reported to promoted leukemia progress by stimulating the dissemination of leukemia cells in vivo." (PMID 32571260, 2020). "The detachment of the chaperone HSPA5 from the luminal portion of the ER integral membrane proteins EIF2AK3, ERN1, and ATF6 is a crucial process in the activation of ER stress in human leukemia and bladder carcinoma cell lines." (PMID 39000233, 2024).
osteosarcoma (21 papers, 2012 to 2025). A usually aggressive malignant bone-forming mesenchymal neoplasm, predominantly affecting adolescents and young adults. "This suggests that a selective complementation of EIF2AK3/PERK signalling deficiency underlies the cooperation between CCT020312 and paclitaxel seen in U2-OS osteosarcoma cells." (PMID 22253692, 2012). "Four ARGs-BRMS, COL4A2, FGF2, and OGT-were used to develop an RFS-predicting model, whereas seven ARGs-CD24, FASN, MMP2, EIF2AK3, ID2, PPARG, and PIK3R3-were used to develop an OS-predicting model in patients with osteosarcoma." (PMID 38217543, 2024).
atherosclerosis (15 papers, 2013 to 2025). A disease characterized by the build-up of fatty material and calcium deposition in the arterial wall resulting in partial or complete occlusion of the arterial lumen. "We found several novel activation pathways between d-flow and atherosclerosis, such as Zn2+-dependent inner mitochondrial membrane metalloendopeptidase OMA1, SR 1078 (a selective agonist of RORα and RORγ) and EIF2AK3 (eukaryotic translation initiation factor 2 alpha kinase 3)." (PMID 38646649, 2024).
depression (12 papers, 2015 to 2025). "Although no study to date has reported a link between EIF2AK3 SNVs and depression, the expression levels of several UPR-related genes and proteins, including EIF2AK3 and PERK, are higher in adults with major depressive disorder." (PMID 38789639, 2024).
insulin-dependent diabetes (12 papers, 2012 to 2025). "Here, mutations in eukaryotic translation initiation factor 2-alpha kinase 3 (also known as PERK), which plays a major role in remediating ER stress, are linked to insulin-dependent diabetes that occurs neonatally or in early infancy." (PMID 34822454, 2021). "Even more intriguing, common variants at PERK contribute to the risk of prediabetes and recessive mutations in the EIF2AK3 gene (encoding PERK) underlie susceptibility to the Wolcott–Rallison syndrome characterized by permanent neonatal insulin dependent diabetes." (PMID 33302345, 2020).
myocardial infarction (10 papers, 2021 to 2025). Gross necrosis of the myocardium, as a result of interruption of the blood supply to the area, as in coronary thrombosis. "Nonetheless, elucidating the precise role of EIF2AK3 in myocardial infarction warrants further research and clarification." (PMID 38818463, 2024).
liver fibrosis (9 papers, 2017 to 2026). "This included genes associated with metabolism (Fabp1, Insr), genes associated with cell stress (Atf6, Ddit3, and Eif2ak3), genes associated with liver fibrosis (Hgf, Sp1, and Timp1) and genes associated with the inflammatory response (Tnf, Ptpn22, and Pparg)." (PMID 28686204, 2017).
lung adenocarcinoma (8 papers, 2015 to 2025). A carcinoma that arises from the lung and is characterized by the presence of malignant glandular epithelial cells. "We concede that ITGB1 and EIF2AK3 have limitations in predicting the prognosis of lung adenocarcinoma." (PMID 36178365, 2022). "Human EIF2AK3 and ITGB-1 specific primers were designed and total RNA was extracted by NCI-H1975 (human lung adenocarcinoma cell) and BEAS-2B (human normal lung epithelial cell)." (PMID 36178365, 2022). "At present, studies have shown that USP4, EIF2AK3 and CTCFL genes are related to the prognosis of lung adenocarcinoma." (PMID 35785155, 2022).
microcephaly (8 papers, 2011 to 2025). A congenital or acquired developmental disorder in which the circumference of the head is smaller than normal for the person's age and sex. "The patients with IER3IP1 mutations presented with more severe microcephaly, permanent neonatal diabetes, and skeletal deformities as compared with patients harboring EIF2AK3 mutations." (PMID 22991235, 2012).
breast tumors (7 papers, 2014 to 2024). "However, a high EIF2AK3:ERO1A ratio predicts a better outcome, indicating cooperation of PERK with the ERO1 pathway in breast tumours." (PMID 35853086, 2022).
progressive supranuclear palsy (7 papers, 2016 to 2025). A rare late-onset neurodegenerative disease characterized by supranuclear gaze palsy, postural instability, progressive rigidity, and mild dementia. "Furthermore, no genetic variants in EIF2AK1 or DELE1 have been found as a risk factor for PD, although genetic studies have reported that EIF2AK3/PERK gene variants are a risk factor for the related neurodegenerative disorder, progressive supranuclear palsy." (PMID 40344059, 2025).
pulmonary fibrosis (7 papers, 2017 to 2025). Chronic progressive interstitial lung disorder characterized by the replacement of the lung tissue by connective tissue, leading to progressive dyspnea, respiratory failure, or right heart failure. "Our data support this notion because there were a reduction of MDMs and decreased production of pro-fibrotic factors in Eif2ak3–/–Lyz2-cre mice, which were protected from pulmonary fibrosis." (PMID 40208691, 2025). "Asbestos-exposed Eif2ak3–/–Lyz2-cre mice were protected from lung fibrosis." (PMID 40208691, 2025).
myocardial ischemia (6 papers, 2021 to 2024). A disorder of cardiac function caused by insufficient blood flow to the muscle tissue of the heart. "Gene-metabolite interaction network analysis revealed the significant roles of key regulatory molecules such as HIF1A, adenosine, TBK1, ATP, NRAS, and EIF2AK3, in the pathogenesis of myocardial ischemia." (PMID 38818463, 2024).
COVID-19 (5 papers, 2022 to 2024). A disease caused by infection with severe acute respiratory syndrome coronavirus 2. "Our work identified that CASP1, CD4, and EIF2AK3 were diagnostic genes of COVID-19 and correlated with immune activity." (PMID 37228369, 2023). "Among them, the expression of CD4 (p < 0.001) in COVID-19 samples was lower than that of control samples, while CASP1 (p = 0.018) and EIF2AK3 (p = 0.012) were higher in COVID-19 samples." (PMID 37228369, 2023). "Taken together, we presented that differentially expressed genes: CASP1, CD4, and EIF2AK3 might be considered as the diagnostic biomarker for COVID-19 and characteristic immunological infiltration could influence the systemic immune microenvironment in the pathogenesis of COVID-19." (PMID 37228369, 2023). "Further CIBERSORT analysis demonstrated that the variations in the immune microenvironment of COVID-19 patients may be correlated with CASP1, CD4, and EIF2AK3." (PMID 37228369, 2023).
hypothyroidism (5 papers, 2016 to 2023). Abnormally low levels of thyroid hormone. "We present a case with a EIF2AK3 p.(Arg902Ter) mutation, additionally complicated by hypothyroidism, impaired renal function, and exocrine pancreas insufficiency, focusing on clinical management." (PMID 31183082, 2019).
Hepatic failure (4 papers, 2010 to 2021). "Screening for genetic mutations in EIF2AK3 is recommended for establishing early diagnosis, providing genetic counselling, and predicting the development of additional clinical features, most importantly hepatic failure." (PMID 30922274, 2019). "The novel genetic alteration causing the absence of the EIF2AK3 protein resulted in insufficient handling of severe endoplasmic reticulum stress, leading to liver failure and demise of the patients." (PMID 32216767, 2020). "Homozygous EIF2AK3 mutations have been found in WRS patients with age at onset up to 2.5 years, in one WRS patient with no bone dysplasia at age 32 years, and hepatic failure has not been reported in all WRS patients." (PMID 21050479, 2010).
Hepatitis (4 papers, 2013 to 2021). Inflammation of the liver. "Here, we report a novel mutation in the EIF2AK3 gene in a 2-year-and-6-month-old girl with neonatal diabetes, pancreatic enzyme deficiency, recurrent hepatitis, primary hypothyroidism and normocytic anemia." (PMID 30922274, 2019). "Wolcott–Rallison syndrome (WRS) is caused by recessive EIF2AK3 gene mutations and characterized by permanent neonatal diabetes (PNDM), skeletal dysplasia, and recurrent hepatitis." (PMID 23759358, 2013). "We report a novel biallelic frameshift mutation p.Gly46AlafsTER19 [AHAE1] in the EIF2AK3 gene in a child with features of WRS, including neonatal diabetes, failure to thrive, recurrent hepatitis, exocrine pancreatic insufficiency, and primary hypothyroidism without any skeletal deformities." (PMID 30922274, 2019).